RIPK1 (receptor interacting serine/threonine kinase 1)
Diseases named in the same sentence as RIPK1 in open-access papers (continued):
Sharing a sentence is not in itself a finding about the gene and the disease.
infection (continued). "While we cannot rule out that PR released during virus entry might target RIPK1 and RIPK2, our data suggest that RIPK1 and RIPK2 cleavage occurs at later stages of infection and depends on transcription of viral genes." (PMID 26297639, 2015). "We found that the inflammation/infection-induced HSPC necroptosis and BM failure in Casp8−/− mice can be completely prevented by Ripk3 deletion; however, the HSC self-renewal defects of Casp8−/− HSCs is mediated by Ripk1-Tbk1-Ifnβ signaling independent of Ripk3." (PMID 38637559, 2024).
neurodegenerative disease (50 papers, 2018 to 2025). A disorder of the central nervous system characterized by gradual and progressive loss of neural tissue and neurologic function. "Many human inflammatory and neurodegenerative diseases are associated with abnormal RIPK1 expression or activity." (PMID 39062098, 2024). "Enhanced activity of RIPK1 in microglia is closely associated with the pathological processes of several human inflammatory and degenerative diseases." (PMID 37665158, 2024). "Reduced TAK1 expression due to aging, acting in conjunction with haploinsufficient mutations in TBK1, can activate RIPK1 and trigger aging-related neurodegenerative diseases." (PMID 36849530, 2023). "Previous studies have shown that RIPK1 is associated with neuroinflammation in many neurodegenerative diseases." (PMID 37239205, 2023). "Elevated RIPK1 kinase activity has also recently been implicated in the pathogenesis of inflammatory and degenerative diseases in mice." (PMID 34990405, 2022). "As upregulated RIPK1 kinase activity is associated with reactive oxygen species (ROS) accumulation in neurodegenerative diseases, we also discuss the current knowledge about the mechanistic links between RIPK1 activation and ROS generation." (PMID 36358573, 2022). "In contrast, mice carrying RIPK1 kinase-dead knockin mutations (K45A, D138N, K584R) showed no abnormalities at baseline and protected against inflammatory and degenerative diseases in mice." (PMID 34990405, 2022). "Necroptosis and RIPK1-mediated inflammation has been implicated in mediating neurodegenerative diseases such as ALS associated with specific mutations in TNFR1 pathway including OPTN and TBK158, 59, 62–65." (PMID 34376696, 2021). "Our results establish a previously undescribed link between RIPK1 and miR-425 and propose miR-425 supplements as a probable therapeutic approach for neurodegenerative disease with neuron loss." (PMID 31383850, 2019). "Upregulated RIPK1 kinase activity and excessive ROS production may collude together, associating with NF-κB activation, to disturb microglial homeostasis in neurodegenerative diseases that still require further detailed studies." (PMID 36358573, 2022). "All these findings suggest excessive ROS may cause microglial dysfunction via regulating RIPK1 and its downstream signaling in neurodegenerative diseases, which requires further detailed investigation in the near future." (PMID 36358573, 2022). "In addition, RIPK1 activation has been reported to be associated with neurodegenerative diseases via inflammation-activating mechanisms." (PMID 34861878, 2021). "These trials represent important steps in advancing promising RIPK1 inhibitors as therapeutic agents for inflammatory and degenerative diseases." (PMID 41019071, 2025). "RIPK1 is an attractive therapeutic target, given that the inhibition of RIPK1 kinase activity has been shown to be effective in animal models of human diseases such as autoimmune and neurodegenerative diseases." (PMID 40456737, 2025). "RIPK1-mediated necroptosis further promotes cell death and inflammation in the pathogenesis of liver injury, skin diseases, and neurodegenerative diseases." (PMID 40007541, 2025). "DNL747 (also known as SAR443060) is a brain-penetrant RIPK1 inhibitor that was being developed by Denali Therapeutics and Sanofi for treatment of neurodegenerative diseases." (PMID 41019071, 2025). "RIPK1 is a critical mediator of microglial dysfunction in neurodegenerative diseases and serves as a potential therapeutic target for treating neurodegenerative diseases." (PMID 41189279, 2025). "Many of these inhibitors are unable to cross it, and those that do often exhibit high liver toxicity deemed unrelated to RIPK1 inhibition, making them unsuitable for the treatment of neurodegenerative diseases, where long-term chronic treatment is required." (PMID 39931431, 2024).
neurodegenerative disease (continued). "In particular, the abundance of RIPK1 protein, which can induce neurodegenerative disease by enhancing the inflammatory response, was significantly elevated in db/db mice (Figure 1A1,A2)." (PMID 37665158, 2024). "Understanding the role of RIPK1 in neuroinflammation in the CNS would provide important insights into the pathogenesis of human neurodegenerative diseases." (PMID 37239205, 2023). "The answers to these questions will help us to further understand the mechanism by which RIPK1 regulates cell death and inflammation and better develop the therapeutic strategies for the treatment of human inflammatory and neurodegenerative diseases." (PMID 36969188, 2023). "Various pre-clinical studies have underscored the potential protective effects of utilizing either a kinase-dead mutant of RIPK1 (RIPK1D138N) or pharmacological RIPK1 inhibitors in diverse neurodegenerative disease models." (PMID 37396657, 2023). "This review will highlight the proinflammatory role of RIPK1 kinase with focus on human neurodegenerative diseases." (PMID 36969188, 2023). "In these previously published studies, it was shown that inhibiting RIPK1 limits neurodegenerative disease." (PMID 36602874, 2023). "As a member of the receptor-interacting protein (RIP) kinase family, RIPK1 has emerged as a target for intervention in inflammatory and neurodegenerative diseases." (PMID 37098514, 2023). "Based on these studies, the development of therapeutic drugs targeting RIPK1 is a new strategy to block cell death in the process of ischemic cardio-cerebrovascular diseases, inflammation, neurodegenerative diseases, and so on." (PMID 36249746, 2022). "RIPK1, a key regulator of necroptosis, has emerged as a promising therapeutic target for neurodegenerative disease." (PMID 35769473, 2022). "Inhibiting RIPK1 kinase activity ameliorates the defects of microglial phagocytosis and the production of neurotoxic cytokines during neurodegeneration, while it remains largely unknown what causes or modulates the activation of RIPK1 in neurodegenerative diseases." (PMID 36358573, 2022). "Via double-staining with a microglial marker or culturing primary microglia derived from transgenic mice, increased RIPK1 protein expression in microglia has further been confirmed in neurodegenerative diseases." (PMID 36358573, 2022). "It have been suggested that RIPK1 inhibitors such as Nec-1 are safe to protect the CNS away from neurodegenerative diseases, partly through the inhibition of TNFR1 signaling transduction, but maintained TNFR2-related neuroprotection." (PMID 36438920, 2022). "The up-regulation of RIPK1 expression and activity in neurodegenerative diseases has been demonstrated by numerous studies both in postmortem human samples and transgenic mice." (PMID 36358573, 2022). "RIPK1 is activated in microglia, and the kinase activity of RIPK1 contributes to microglial dysfunction in multiple neurodegenerative diseases." (PMID 36358573, 2022). "The expression and kinase activity of RIPK1 is indeed elevated in microglia in the context of neurodegenerative diseases." (PMID 36358573, 2022). "In human individuals, loss-of-function mutations in the genes that encode these key components of complex I lead to inflammatory and neurodegenerative diseases, which is largely stemmed from aberrant activation of RIPK1." (PMID 39872161, 2022). "Inhibitors of RIPK1 kinase have been advanced into human clinical studies for developing new therapies of various devastating human inflammatory and degenerative diseases that still lack effective treatments." (PMID 34075030, 2021). "In human neurodegenerative diseases, inhibition of caspase-8 favors necroptosis by preventing cleavage and inactivation of RIPK1." (PMID 34753914, 2021). "Human genetics reveals that perturbation of RIPK1 signaling leads to many severe inflammatory and degenerative diseases, including autoinflammatory disorders and ALS." (PMID 34862394, 2021).
neurodegenerative disease (continued). "Previous studies based on Nec-1 demonstrated that inhibition of RIPK1 blocked the cell death including necroptosis and apoptosis in an animal model of degenerative diseases." (PMID 29980212, 2018). "Receptor-interacting protein kinase 1 (RIPK1), which regulates cell death and survival pathways, is a promising therapeutic target for the treatment of several autoimmune, inflammatory, and neurodegenerative diseases, having important roles in inflammation, apoptosis, and necroptosis." (PMID 41019071, 2025). "The role of RIPK1 in neurodegenerative diseases has recently been reported." (PMID 37329446, 2023). "Therefore, the possibility is high that RIPK1-mediated neuroinflammation promotes protein misfolding and aggregation in many neurodegenerative diseases." (PMID 36766759, 2023). "Collectively, these studies suggest that targeting RIPK1 may offer therapeutic potential in the management of neurodegenerative diseases." (PMID 37396657, 2023). "Disturbed post-translational modifications or translation of mRNA in neurodegenerative diseases might also lead to the accumulation of RIPK1 protein." (PMID 36358573, 2022). "Above all, these findings suggest that targeting multiple cell death key sites would be more effective than single therapy approach and targeting RIPK1 may provide an promising therapeutic strategy for the treatment of neurodegenerative diseases." (PMID 34922574, 2021). "Receptor interacting protein kinase 1 (RIPK1) regulates cell death and inflammatory responses downstream of TNFR1 and other receptors, and has been implicated in the pathogenesis of inflammatory and degenerative diseases." (PMID 32269263, 2020). "Necroptosis is an emerging field closely related to apoptosis and targeting RIPK3 and RIPK1 may help to overcome therapeutic hurdles in the treatment of inflammatory and neurodegenerative diseases." (PMID 29980212, 2018). "Recent findings indicate that both genetic mutations and non-genetic factors influencing RIPK1 activity can lead to a range of inflammatory and degenerative diseases, highlighting the necessity for precise regulation of RIPK1 function in maintaining human health." (PMID 39062098, 2024). "Therefore, the strategy of RIPK1 inhibition in astrocytes may be more widely applied to the treatment of a variety of neurodegenerative diseases characterized and involving A1 reactive astrocyte activation." (PMID 37239205, 2023). "With growing evidence that RIPK1 plays a critical role in modulating microglia activity in neurodegeneration, there is an increasing number of RIPK1 inhibitors being investigated in human clinical studies for treating neurodegenerative diseases, such as ALS and AD." (PMID 36358573, 2022). "Our study suggests that inhibition of RIPK1 may reduce neuroinflammation and the accumulation of misfolded proteins in neurodegenerative diseases that are not genetically connected with mutations in the genes that directly regulate the activation of RIPK1." (PMID 34376696, 2021). "Necroptosis, a major driver of neuronal cell death and microglial dysfunction in neurodegenerative diseases, is initiated by the subsequential TNF-α induced activation of RIPK1, RIPK3, and MLKL." (PMID 36358573, 2022). "Transgenic models and pharmacologic inhibition have demonstrate that RIPK1, RIPK3 and MLKL are involved in many neurodegenerative diseases." (PMID 34922574, 2021). "Regulated necrosis or necroptosis, mediated by receptor-interacting kinase 1 (RIPK1), RIPK3 and pseudokinase mixed lineage kinase domain-like protein (MLKL), contributes to the pathogenesis of inflammatory, infectious and degenerative diseases." (PMID 32123582, 2020).
bacterial infection (10 papers, 2017 to 2025). "It is now known that TAK1 is a negative regulator of PANoptosis, and that inhibition of TAK1 combined with innate immune priming, such as LPS treatment or bacterial infection, mediates RIPK1-dependent PANoptosis." (PMID 37557956, 2023). "Bacterial infection increased the expression of RIPK1/3 and MLKL." (PMID 38292869, 2024). "However, to counteract the host response to bacterial infection, Shigella employs OspD3 to target and cleave the RHIM domains of RIPK1 and RIPK3, thereby degrading RIPK1 and RIPK3 and inhibiting necroptosis in host cells." (PMID 38933265, 2024). "In contrast, pretreatment with Nec-1 to inhibit RIPK1 failed to reduce cell death after bacterial infection; moreover, cell death after Nec-1 incubation tended to increase." (PMID 30814594, 2019). "In our present study, CDK9 inhibition or knock-down significantly reduced RIPK1, RIPK3 and TRIF levels after bacterial stimulation, thereby may reduce necroptosis during bacterial infection." (PMID 31758083, 2019). "Since MK2 is activated under various stress conditions that stimulate p38, such as UV irradiation, heat shock, oxidative stress, hyperosmolarity, bacterial infection, and different cytokines, it is tempting to speculate that MK2 regulates RIPK1 under many of these stress conditions." (PMID 28506461, 2017).
cardiovascular diseases (8 papers, 2018 to 2024). "Due to its crucial role in cell death and inflammation, RIPK1 has implicated as a potential therapeutic target for cardiovascular diseases." (PMID 34760938, 2021). "Taken together, RIPK1/3 and necroptosis play important roles in the pathophysiology of aging-associated cardiovascular disease, targeting necroptosis pathway may provide therapeutic benefit in the treatment of cardiovascular disease." (PMID 39872161, 2022). "While RIPK1 deficient animals die shortly after birth, a consequence thought to be due to altered NF-kβ signaling and altered patterns of cell death, the role of RIPK1 in cardiovascular disease has been able to be explored through the use of targeted inhibitors." (PMID 33142926, 2020). "Recently, more and more studies show great interest in the mechanisms and the regulator of RIPK1/3-mediated inflammatory response and in the physiopathogenesis of cardiovascular diseases." (PMID 34867386, 2021). "As a key regulator of necroptosis, RIPK1/3 can participate in the occurrence of cell death and inflammation in cardiovascular diseases." (PMID 34867386, 2021). "In this review, we discuss the latest progress in this fast-moving field, with a focus on the signaling pathways, and the physiological and pathological implications of RIPK1/3 mediated necroptosis, and the latent therapeutic targets in diverse cardiovascular diseases." (PMID 34867386, 2021). "Research into the role of RIPK1 and RIPK3 in cardiovascular disease and the potential to translate inhibitor studies from the bench to the bedside must continue to be aggressively pursued." (PMID 33142926, 2020). "In this review, we provide an overview of the current evidence supporting a pathologic role of RIPK1 and RIPK3 in cardiovascular disease." (PMID 33142926, 2020). "Moreover, we highlight the evidence behind the efficacy of targeted RIPK1 and RIPK3 inhibitors in the prevention and treatment of cardiovascular disease." (PMID 33142926, 2020). "Specifically, the damaging role of two kinase proteins pivotal in the necroptosis pathway, Receptor Interacting Protein Kinase 1 (RIPK1) and Receptor Interacting Protein Kinase 3 (RIPK3), in cardiovascular disease has become a subject of great interest and importance." (PMID 33142926, 2020).
neurological diseases (8 papers, 2020 to 2025). "Our studies demonstrate that [11C]CNY‐10 is a promising PET radioligand for RIPK1 imaging in AD and potentially in other neurological disorders." (PMID 38923244, 2024). "Targeting Ripk1 in the treatment of neurological diseases may help inhibit multiple cell death pathways and ameliorate neuroinflammation." (PMID 38225547, 2024). "Necrostatin-1 (Nec), as the first specific inhibitor of RIPK1, has been extensively demonstrated to possess noticeable effects on inhibiting necroptosis in various diseases, including inflammatory cardiovascular, neurological diseases, etc.." (PMID 37462822, 2023). "RIPK1, RIPK3, and MLKL play a pivotal role in inducing necroptosis, and RIPK1, RIPK3, and MLKL upregulation could be common in many neurological diseases, including CIR injury." (PMID 34905731, 2021).
inflammation (5 papers, 2020 to 2025). Aberrant reaction of the microcirculation characterized by movement of fluid and leukocytes from the blood into extravascular tissues. "Treating aged WT or adult Sod1−/− mice with necrostatin-1s, a RIPK1 inhibitor, reduces liver inflammation and MASH pathology, underscoring the necroptosis pathway’s role in age-related liver inflammation and MASH." (PMID 39930289, 2025).
breast (3 papers, 2021 to 2023). "However, the potential regulation of RIPK1 by Caspase 6 in liver IR model is virtually unexplored." (PMID 37828624, 2023). "Our findings underscore a novel mechanism of Caspase 6 mediated RIPK1-IκBα interaction in regulating macrophage NEK7/NLRP3 function and hepatocytes ferroptosis, which provides therapeutic targets for clinical liver IR injury." (PMID 37828624, 2023).
metabolic disease (3 papers, 2022 to 2025). A congenital disorder (due to inherited enzyme abnormality) or acquired (due to failure of a metabolically important organ) disorder resulting from an abnormal metabolic process. "Previous studies, including our own, have linked RIPK1’s kinase activity to the pathogenesis of metabolic diseases like NASH, indicating a metabolic regulatory role of RIPK1 kinase." (PMID 39886919, 2025). "A large body of evidence places RIPK1/3-driven caspase-8 or MLKL signaling upstream of NLRP3 inflammasome activity in a range of disease settings, yet their contribution to inflammasome activity in metabolic disease is less clear." (PMID 39532538, 2025).
animal disease (2 papers, 2019 to 2022). "Therapeutically, the inhibition of RIPK3 or RIPK1 exhibited anti-inflammatory effects in animal disease models, suggesting that the inhibitors of these kinases may have a therapeutic potential to treat inflammatory injuries." (PMID 35769473, 2022).
central nervous system disorder (2 papers, 2020 to 2024). A disease involving the central nervous system. "Necrostatin-1 (Nec-1) was first developed as a receptor-interacting protein kinase 1 (RIPK1) inhibitor and has been used to treat other acute central nervous system disorders that feature necroptosis as a mode of cell death." (PMID 33077863, 2020).
genetic diseases (2 papers, 2019 to 2025). "While there is no direct evidence currently that the inflammation in these human genetic disorders is RIPK1-dependent, the mouse models strongly suggest that the pathology in these genetic disorders is caused by a failure in the early checkpoint." (PMID 31457011, 2019).
blood cancers (1 paper, 2023). "RIPK1 (receptor-interacting serine/threonine-protein kinase 1) has been observed to be dysregulated and implicated in the pathogenesis of multiple solid cancers, of which, however, the roles in blood cancers are quite unclear." (PMID 37462822, 2023).
bone disorder (1 paper, 2021). "In this study, we found that the RIPK1/RIPK3/MLKL pathway was involved in alcohol-induced bone disorders and osteoblast necroptosis both in vivo and in vitro." (PMID 34745415, 2021).